OR13C9 (olfactory receptor family 13 subfamily C member 9)
Description:
Odorant receptor.
Synonyms: OR37L; OR9-13
Tractability: Antibody: its Gene Ontology location is reachable by antibodies, with high confidence; UniProt places it where antibodies can reach, with medium confidence; UniProt predicts a signal peptide or a membrane-spanning region.
Gene: Protein-coding gene on chromosome 9 (104,617,248 to 104,618,204, reverse strand). Ensembl gene ENSG00000136839.
Subcellular location: Cell membrane
Subcellular location (Human Protein Atlas): Plasma membrane; Nucleoplasm
Pathways (Reactome):
Sensory Perception: Expression and translocation of olfactory receptors
Gene Ontology:
Molecular function: olfactory receptor activity; G protein-coupled receptor activity
Biological process: detection of chemical stimulus involved in sensory perception of smell; G protein-coupled receptor signaling pathway
Cellular component: nucleoplasm; plasma membrane; membrane
Genetic constraint (gnomAD): Loss-of-function variants: 1 observed, 0.16 expected, observed/expected ratio (o/e) 6.19. That is too few expected variants to judge how well the gene tolerates losing a copy. Missense variants: 368 observed, 392.67 expected, observed/expected ratio (o/e) 0.94, 90% interval 0.86 to 1.02. Synonymous variants: 133 observed, 137.04 expected, observed/expected ratio (o/e) 0.97, 90% interval 0.84 to 1.12.
Homologues: Orthologues: macaque OR13C9 (94% identical), dog OR13C2 (93% identical), dog OR13C2B (89% identical), rat Or13c9 (83% identical). Paralogues in human: OR13C2 (92% identical), OR13C5 (86% identical), OR13C4 (65% identical), OR13C3 (64% identical), OR13C8 (64% identical), OR2S2 (64% identical), OR13D1 (59% identical), OR2K2 (57% identical), OR13J1 (51% identical), OR2F1 (47% identical), OR2G3 (47% identical), OR5V1 (47% identical), and 80 more.